FGG (fibrinogen gamma chain)
Diseases named in the same sentence as FGG in open-access papers (continued):
Sharing a sentence is not in itself a finding about the gene and the disease.
pneumonia (1 paper, 2021). An acute, acute and chronic, or chronic inflammation focally or diffusely affecting the lung parenchyma, caused by an infection in one or both of the lungs (by bacteria, viruses, fungi, or mycoplasma.). "Among genes upregulated in ACE2-expressing AT2 cells, we identified genes that are highly pertinent to lung epithelial biology and disease such as HHIP (lung branching and COPD), FGG (fibrosis, pneumonia, and inflammation), and C4BPA (complement system, pneumonia, and infection)." (PMID 33809063, 2021).
psychosis (1 paper, 2024). "C4B, Complement C4-A (C4A), Complement C2 (C2), A2M, LRG1, and the Fibrinogen alpha, beta, and gamma chains (FGA, FGB, and FGG) were differentially expressed between those who transitioned to psychosis and those who did not, adjusting for age, sex, and study." (PMID 38243809, 2024).
renal fibrosis (1 paper, 2023). A final common manifestation of a wide variety of chronic kidney diseases characterized by glomerulosclerosis and tubulointerstitial fibrosis. "As Epithelial-mesenchymal transition (EMT) is considered as an important step of renal fibrosis, we propose that, as a primary component of fibrinogen, FGG may also participate in the transition of renal tubular epithelial cells through EMT and promote renal interstitial fibrosis." (PMID 36941570, 2023).
rheumatoid arthritis (1 paper, 2019). A chronic, systemic autoimmune disorder characterized by inflammation in the synovial membranes and articular surfaces. "FGG has additionally been reported to be expressed at higher levels in rheumatoid arthritis synovial fluid, something that has also been shown for Alpha-1-B Glycoprotein (A1BG), although little else is known about A1BG function." (PMID 30770760, 2019).
systemic lupus erythematosus (1 paper, 2021). An autoimmune multi-organ disease typically associated with vasculopathy and autoantibody production. "C3, CFH, SERPING1, FGA, and FGG were significantly enriched in the “complex and coagulation cascades pathway,” C3 was also enriched in the “systemic lupus erythematosus” pathway, and PRB1 in the “salivary secretion” pathway." (PMID 34516718, 2021).
type I plasminogen deficiency (1 paper, 2022). "Further, SNPs rs73015965 (PLG K38E) and rs148685782 (FGG A108G) associated with type I plasminogen deficiency and reduced levels of fibrinogen, respectively, were common only in the EUR population." (PMID 35337356, 2022).
ZIKV infection (1 paper, 2022). "Our observation of alpha-1 antitrypsin, fibrinogen gamma chain, fibronectin being localized in the stroma of the tissue suggests that ZIKV infection of the placenta is also activating a restructuration of ECM by activating these proteins." (PMID 34264436, 2022). "Colocalization of fibrinogen gamma chain with the labeled macrophages and fibronectin location in the stroma in ZIKV infection further supports our proteomics results of the coagulation pathway being active." (PMID 34264436, 2022). "Since the proteins fibrinogen-α (FGA), fibrinogen-β (FGB), and fibrinogen-γ (FGG) are overexpressed, and these are precursors of fibrin, a major component of blood clots, these data indicate that the coagulation cascade is being activated in the placental tissue upon ZIKV infection." (PMID 34264436, 2022).
tumor (28 papers, 2015 to 2025). "We further explored the associations between the specific prognostic markers FGG and tumor progression, immune invasion, and the tumor cell stem index to identify potential LUSC-specific survival prognostic biomarkers and therapeutic targets." (PMID 37841237, 2023). "We detected the significant downregulation of the expression of genes encoding acute phase proteins (e.g., FBG, FGA, and FGG) and tumor-associated genes such as SERPINC1 and F2." (PMID 38203636, 2023). "Knockdown of FGG caused functional changes in LUSC tumor progression at the tumor cell level, significantly inhibited the proliferation and clonogenesis ability of NCI-H520 and LTEP-s cells, and blocked the cell cycle in the S phase." (PMID 37841237, 2023). "Among them were genes associated with blood clotting (FGA, FGG) and genes associated with changes in the immune characteristics of a tumor (ENAM, IGFBP1, IL6)." (PMID 36028558, 2022). "Notably, disrupting the ICAM-1–FGG interaction using ICAM-1Δ8-22 mutation showed similar tumor inhibition as knockdown of ICAM-1 or FGG." (PMID 39168965, 2024). "Fibrinogen beta chain (FGB), filamin-A (FLNA), and fibrinogen gamma chain (FGG) were associated with homotypic cell-cell adhesion and regulation of substrate adhesion-dependent cell spreading, which were closely related to the invasion and metastasis of tumor cells." (PMID 37124724, 2023). "The fibrinogen subunits FGB and FGG play essential roles in the tumor microenvironment by promoting thrombosis, which has been linked to HCC progression." (PMID 40307890, 2025). "The COOH-terminal globular domain of fibrinogen gamma chain participated in inducing apoptosis of endothelial cells and blocked tube formation of endothelial cells, suppressed tumor growth and metastasis." (PMID 39227068, 2024). "Only 1 specimen was observed FGG staining not only on tumor cells but also on stroma cells, indicating that FGG is predominantly produced by NSCLC tumor cells and is sufficient to maintain malignant cell survival during NSCLC progression." (PMID 39168965, 2024). "FGG was shown to be overexpressed in both HCC and HepG2, matching our results, and increased levels of plasma fibrinogen correlated with the presence of tumor thrombosis and was associated with higher clinical stages of HCC." (PMID 39596661, 2024). "Subsequently, we evaluated the scores of 22 kinds of tumor immune cell infiltration in LUSC patients according to the expression of FGG and found that FGG was significantly correlated with 10 kinds of immune cell infiltration, including M1 macrophages." (PMID 37841237, 2023). "In vitro experimental models confirmed that LUSC-specific DEG FGG expression was significantly higher in tumor cells and correlated with immune tumor progression, immune infiltration, and stem index." (PMID 37841237, 2023). "FGB and FGG, components of the extracellular matrix protein fibrinogen, are crucial for wound healing and hemostasis and function in tumor angiogenesis and metastasis." (PMID 37953280, 2023). "Fibrinogen is an extracellular matrix protein composed of three polypeptide chains, fibrinogen alpha (FGA), beta (FGB), and gamma (FGG), and is involved in tumor angiogenesis and metastasis." (PMID 36233212, 2022). "In the coagulation cascade pathway, the mRNA level of FGG and the elevated plasma fibrinogen level are related to the clinical stage, tumor thrombosis, and prognosis of HCC." (PMID 36471393, 2022). "The size of the FGG-KD xenograft tumors was significantly smaller than those in the NC group, and the tumor weights in the FGG-KD group was also remarkably lower than the NC group." (PMID 33995485, 2021). "IHC results showed that the FGG staining was weakened and the number of Ki67 positive cells were significantly decreased in the FGG-KD group, all of those indicating that tumor growth has been impactful inhibited." (PMID 33995485, 2021).
tumor (continued). "However, recent studies suggest that FGG plays a crucial role in tumor progression, particularly in promoting angiogenesis, metastasis, and immune suppression." (PMID 41200166, 2025). "It has been reported that the dysregulation of FGG but not other chains of FG frequently occurs in many malignant cancer types, emphasizing that FGG may function beyond the structural domain of FG in the tumor environment." (PMID 39168965, 2024). "SVIL and FGG also have corresponding roles in the tumor process." (PMID 36160006, 2022). "Indeed, FGG is reported to promote tumor cell migration and invasion in hepatocellular carcinoma cells, as well as to maintain tumor cell proliferation and disease progression in prostate cancer, emphasizing diverse and complex functions of FG components in the tumor microenvironment." (PMID 39168965, 2024). "Taken together, these evidences confirm that these HEMTIRGs (CRISP3, PAX7, FGG, and DCD) are closely related to hypoxia, EMT, and tumor immunity, which in turn contribute to the regulation of BC pathogenesis and prognosis." (PMID 41200166, 2025). "In contrast, GLYs, such as the fibrinogen family (FGA, FGB, and FGG), fibronectin (FN1), transforming growth factor beta-induced protein (TGFβI), and tenascin-C (TNC), had an increased presence in tumor tissues." (PMID 40032993, 2025). "This study established a seven-gene profile (FGG, C3, FGA, JUN, CST3, CPSF4, and HIST1H2BH) prognostic stratification system demonstrated in LUSC based on Tumor Progression, Immune Infiltration, and Stem Index." (PMID 37841237, 2023). "To further evaluate the function of FGG on tumor growth in vivo, we established a xenograft mouse model using DU145 cells that stably express shRNA knocking down FGG expression (KD) or an empty vector control (NC)." (PMID 33995485, 2021). "Taken together, our study demonstrates the specific changes in serum FGG levels in CRPC patients and systematically elucidated the effects of FGG on tumor progression in vitro and in vivo." (PMID 33995485, 2021). "Meanwhile, the hub genes from the DEGs between T and LM groups (ALB, FGG, AHSG, TF, and GC) also showed marked alterations in the correlations, indicating potential mechanisms involved in the tumor metastasis." (PMID 32496505, 2020). "Our results suggest that FGG can affect the tumor process of LUSC cells, as shown by the proliferation, cloning, invasion, and migration of NCI-H520 and LTEP-s being significantly inhibited following FGG knockdown." (PMID 37841237, 2023). "FGG and integrin β2 bind to distinct binding sites in ICAM-1, shedding light on the possibility of exploiting neutralizing antibodies or compounds to specifically obstruct ICAM-1‒FGG interaction without affecting integrin β2‒ICAM-1 binding involved in anti-tumor immune responses." (PMID 39168965, 2024). "Notably, tumors of shICAM-1 and shFGG groups grew slower and displayed spontaneous regression on day 6, followed by a quick and significant shrink in tumor volume in next days, indicating the death of tumor cells when ICAM-1 or FGG was absent." (PMID 39168965, 2024). "As no expression for aldolase C, FGG (Fibrinogen gamma chain), Prx-cis (periaxin), prothrombin, VDAC (voltage-dependent anion channels), and LRG (leucine-rich alpha-glycoprotein) was found in tumor cells, they were considered negative markers for BCC." (PMID 27578920, 2016). "The expressions of APOB, FGA, FGG, APOA1, and F2 were significantly down-regulated in the TCGA-LIHC cohort (P<0.05), but SERPINC1 levels were not significantly different between normal and tumor tissues (P>0.05)." (PMID 33834191, 2021).
cancer (16 papers, 2014 to 2024). A tumor composed of atypical neoplastic, often pleomorphic cells that invade other tissues. "Fibrinogen is a protein that is encoded by three different genes (FGA, FGB, FGG), two of which were upregulated in plasma samples from cancer patients in the current study." (PMID 39146279, 2024). "FGG encodes for fibrinogen gamma chain that has been linked to enhanced invasion of lung and other cancer cells." (PMID 33960931, 2021). "FGG, which encodes the gamma chain of fibrinogen, is down-regulated in the epithelial-to-mesenchymal transition, an important mechanism in cancer metastasis." (PMID 31506599, 2019). "Our bioinformatics modeling demonstrated that FGG as a risk prognosticator is of significant research value in LUSC, and the results of subsequent in vitro experiments are consistent with reports of abnormal expression of FGG mRNA in various cancers." (PMID 37841237, 2023). "High expression of CPS1, FGG, and GPX2 has been frequently associated with poor prognosis of various cancers." (PMID 33493519, 2021). "Among them, five genes (FGG, MYH15, STARD4, SYTL4, and TMEM267) were first associated with cancer procession, while the other three (KRT81, KRT6A, and KRT13) have previously been confirmed to be related to cancer metastasis and migration." (PMID 37817112, 2023). "Finally, we investigated the expression of fibrinogen gamma chain, a molecule essential for platelet aggregation, whose synthesis has been elevated in patients with cancer and cachexia." (PMID 37701438, 2023). "Taken together, our study demonstrates that FGG binds to ICAM-1 on NSCLC cell surface and triggers anti-apoptotic signaling in cancer cells, therefore protects cancer cell from apoptosis." (PMID 39168965, 2024). "NTS is highly positively correlated with the expression of the cancer-promoting factors CPS1, FGG, and GPX2 in a subgroup of NSCLC." (PMID 33493519, 2021). "Examination of the first gene list (ever vs. never smokers) revealed that one of our seven signature genes, FGG, was also upregulated in ever smokers without cancer." (PMID 31506599, 2019).
infection (9 papers, 2014 to 2025). The state of being infected such as from the introduction of a foreign agent such as serum, vaccine, antigenic substance or organism. "ELISA assay confirmed the elevation of FGB and FGG in OBI samples, suggesting their potential as biomarkers for distinguishing OBI from HBsAg-positive infection." (PMID 39600945, 2024). "On the other hand, 24 genes were significantly upregulated by infection in the R line of the HSF flock, such as CD19, CD22, CD79B, two complement-related genes CFI and CR2 (complement C3d receptor 2), FGG, and FGA (fibrinogen alpha chain)." (PMID 30678719, 2019). "Nevertheless, the infection was also able to repress extracellular exosome-related genes, such as complement C7 (C7) in the R line of the HSF flock, and fibroblast growth factor 9 (FGF9), cadherin 16 (CDH16), and FGG, in the R line of the TSF flock." (PMID 30678719, 2019).
cardiovascular disease (4 papers, 2017 to 2023). "In addition, serum FGG has been reported to predict cardiovascular disease." (PMID 37308827, 2023). "In addition, some research findings suggested that the fibrinogen level and genetic variation in the FGG gene may influence arterial stiffness, which can be used to predict cardiovascular disease." (PMID 28629174, 2017).
infectious disease (2 papers, 2022 to 2024). A disorder directly resulting from the presence and activity of a microbial, viral, or parasitic agent in humans. "Interestingly, hub genes from age groups of 0-20 years old and 71-100 years old, namely, ARPC2, UBB, FGB, and FGG, are mostly involved in infectious diseases and the immune system." (PMID 36084955, 2022).
myopathy (1 paper, 2015). A disease of the muscle in which the muscle fibers do not function properly. "Birds suffering from this myopathy exhibit down-regulation of eight hemostatic genes (A2M, FGA, FGB, FGG, KNG1, SERPINC1 and VWF) and up-regulation of four other coagulation genes (F5, F10, PROS1 and F2R)." (PMID 26445145, 2015).
neurodegenerative disease (1 paper, 2025). A disorder of the central nervous system characterized by gradual and progressive loss of neural tissue and neurologic function. "FGG, which has been recognized as the marker for inflammatory responses, plays a role in neurodegenerative diseases." (PMID 40673140, 2025).
neurological disease (1 paper, 2021). "Among the affected genes after OGD/R in human cerebral organoids, transthyretin (TTR), alpha-2-HS-glycoprotein (AHSG), and fibrinogen gamma chain (FGG) were found to be related to neurological disease." (PMID 34168538, 2021).
FGG also shares sentences with these, for which no sentence is quoted: gastric cancer (3 papers); myocardial infarction (2); renal cell carcinoma (2); stomach cancer (2); viral infection (2); age (1); Alagille syndrome (1); alopecia (1); Alzheimer disease (1); anemia (1); atherosclerosis (1); Brain atrophy (1); chronic obstructive pulmonary disease (1); Cognitive impairment (1); colitis (1); colon cancer (1); colorectal adenocarcinoma (1); connective tissue disorder (1); dementia (1); endocarditis (1); familial amyloid polyneuropathy (1); glioma (1); heart diseases (1); hematological disease (1); Hepatic fibrosis (1); Hypercholesterolemia (1); Hypertension (1); hypobetalipoproteinemia (1); Miscarriage (1); morbid obesity (1).
A further 15 diseases each share a sentence with FGG in 1 paper.